INAFM2 (InaF motif containing 2)
Synonyms: LINC00984; OGU1
Tractability: Antibody: UniProt predicts a signal peptide or a membrane-spanning region.
Gene: Protein-coding gene on chromosome 15 (40,323,692 to 40,326,715, forward strand). Ensembl gene ENSG00000259330.
Subcellular location: Membrane
Gene Ontology:
Cellular component: membrane
Genetic constraint (gnomAD): Loss-of-function variants: 5 observed, 5.39 expected, observed/expected ratio (o/e) 0.93, 90% interval 0.48 to 1.75. That is too few expected variants to judge how well the gene tolerates losing a copy. Missense variants: 186 observed, 194.54 expected, observed/expected ratio (o/e) 0.96, 90% interval 0.85 to 1.08. Synonymous variants: 113 observed, 101.1 expected, observed/expected ratio (o/e) 1.12, 90% interval 0.96 to 1.31.
Homologues: Orthologues: chimpanzee INAFM2 (100% identical), pig INAFM2 (93% identical), mouse Inafm2 (92% identical), guinea pig INAFM2 (87% identical), rat Inafm2 (50% identical), tropical clawed frog INAFM2 (42% identical).
Diseases named in the same sentence as INAFM2 in open-access papers:
INAFM2 is named in the same sentence as 5 diseases in open-access papers, as found by Europe PMC text mining. Sharing a sentence is not in itself a finding about the gene and the disease.
INAFM2 shares sentences with these, for which no sentence is quoted: acute coronary syndrome (1 paper); cancer (1); familial partial lipodystrophy (1); tumours (1); type 2 diabetes (1).